CXCL12 (C-X-C motif chemokine ligand 12)
Diseases named in the same sentence as CXCL12 in open-access papers (continued):
Sharing a sentence is not in itself a finding about the gene and the disease.
tumor (continued). "Recent evidence suggests that CXCR4-mediated proliferation and metastasis of tumor cells is regulated by CXCR7 through its scavenging of chemokine CXCL12." (PMID 25884570, 2015). "In the course of tumor growth, the CXCR4 ligand CXCL12 is mainly produced by the stromal cells forming the tumor niche." (PMID 26083776, 2015). "We extend our model to analyze CXCL12 gradient formation in a tumor environment and find that short distance, steep gradients characteristic of the CXCL12-γ isoform are effective at driving chemotaxis." (PMID 25909600, 2015). "CAFs secrete monocyte chemotactic protein 1 (MCP1/CCL2) and stromal-cell-derived factor 1 (SDF1), also known as CXCL12, which are involved in the recruitment of myeloid-derived suppressor cells (MDSCs) and tumor-associated macrophages (TAMs)." (PMID 28536400, 2015). "The CXCL12/CXCR4 axis also plays an important role in the PCa progression through tumor cell migration and invasion." (PMID 25605248, 2015). "As is true for CXCL12, the source of S1P and the importance of its effects on tumor stroma remain to be established." (PMID 29061949, 2015). "Blocking receptors for the chemokines CXCL1 and CXCL12 retards tumor growth, reduces invasion, eliminates CSCs, and restores drug sensitivity." (PMID 25871388, 2015). "It is widely accepted that the CXCR4/CXCL12 axis underlies the decreased chemosensitivity and disease progression, by directing CXCR4-expressing tumor cells through concentration gradients of CXCL12 to reside in protective niche (such as BM and lymph nodes)." (PMID 25704881, 2015). "The CXCL12-induced CXCR4-mediated intracellular signaling enhances tumor growth, cancer cell survival, and metastasis." (PMID 26083776, 2015). "Among the secreted factors that mediate the tumor promoting effect of CAFs is CXCL12 (SDF1), a chemokine that can induce angiogenesis and enhance the proliferative capacity of cancer cells." (PMID 26501341, 2015). "This receptor mediates the homing of tumor cells to specific organs that express the ligand, CXCL12, for this receptor and plays an important role in tumor growth, invasion, metastasis and angiogenesis." (PMID 25503960, 2015). "Many studies had demonstrated that CXCR4/CXCL12 axis plays an important role in regulating metastasis of CXCR4 positive tumor cells to the organs expressing CXCL12." (PMID 26526157, 2015). "Activation of the CXCR4/CXCL12 axis can lead to tumor proliferation and can promote neoangiogenesis, cancer cell invasion and metastasis, and EMT." (PMID 26437222, 2015). "Our findings also suggest that ANGPTL2 increases bone metastasis by up-regulating CXCR4 in primary tumor cells, thereby enhancing their responsiveness to bone tissue-secreted CXCL12." (PMID 25773070, 2015). "Other studies suggest that chemokine C-X-C motif receptor type 4 (CXCR4) binding to CAF-secreted chemokine C-X-C motif ligand 12 (CXCL12) initiates carcinoma derived MMP-9 secretion in the tumor microenvironment." (PMID 25734659, 2015). "Based on these studies we conclude that there is a complex interaction between CXCR4 expressed on tumor cells with CXCL12 present in the surrounding stroma." (PMID 26161302, 2015). "In this context, the CXCR4/CXCL12 interaction has been demonstrated to direct CXCR4+ tumor cells to the sites for the development of metastasis." (PMID 26091099, 2015). "The chemokine CXCL12 (SDF-1) acts as a chemoattractant to the CXCR4 receptor-positive primary tumor cells, and drives them toward secondary metastatic sites." (PMID 26377541, 2015). "Metastasis did not require cell-autonomous co-expression of both receptors; instead, the co-implantation of CXCR7- and CXCR4-positive tumor cells was sufficient to promote the metastasis of the latter, and this involved scavenging of extracellular CXCL12." (PMID 25884570, 2015). "The CXCL12/CXCR4 axis plays a crucial role in tumor development, by many different proposed mechanisms." (PMID 26259237, 2015).
tumor (continued). "Among the genes that were relatively upregulated in the bevacizumab-resistant tumours compared with the control tumours, we focused on CXCL12, the ligand of CXCR4." (PMID 26635184, 2015). "For example, the CXCL12/CXCR4 axis plays an important role in tumor cell extravasation and tissue-specific homing." (PMID 25897429, 2015). "We showed extracellular matrix modifications of the tumor and upregulation of factors generally secreted by CAFs such as CXCL12, ASPN and OLFML3." (PMID 26437222, 2015). "First, CXCR4 is essential for metastatic spread to organs where CXCL12 is expressed and thereby allows tumour cells to access cellular niches that favour tumour cell survival and growth." (PMID 25598217, 2015). "CXCL12 expression in tumor buds was found to be correlated with liver metastases and was an independent prognostic marker." (PMID 25806371, 2015). "As nodal metastases were detected in 90.5% of the patients with HPV-positive and 66.7% of the patients with HPV-negative tumor samples, the differences in CXCL12 levels most likely reflect this fact." (PMID 25949860, 2015). "Decreased CXCL12 expression further led to dissemination of CXCR4+ tumor cells to distant lymphatic tissues with higher CXCL12 expression." (PMID 25704881, 2015). "Consistently, the immunofluoresence signal for CXCL12 including both mouse and human molecules was observed in both the orthotopic tumor and the metastatic lesions in the lung." (PMID 26083776, 2015). "To evaluate the difference of the expression levels of CXCL12 between the orthotopic tumor and the lung, we quantified the expression levels of Cxcl12 mRNA." (PMID 26083776, 2015). "Meanwhile, overexpression of miR-222 inhibited TAM chemotaxis, and miR-222 in TAMs inhibited 4T1 tumor growth by targeting CXCL12 and inhibiting CXCR4." (PMID 26689540, 2015). "Previous studies have also shown that the CXCR4 ligand CXCL12 is able to induce integrin activation, resulting in increased tumor cell adhesion and metastasis in SCLC." (PMID 25671300, 2015). "Although expression of CCL5, CXCL9, CXCL10 and CXCL12 were also consistently detected in the tumours, expression of each was also detected in spleen and lymph node." (PMID 25495686, 2015). "High expression of CXCR4 and CXCL12 has been observed in various carcinomas, resulting in increased cell migration and tumor angiogenesis." (PMID 26560447, 2015). "We additionally noted that CXCL12 expression appeared higher in tumor tissue from patients that had received neo-adjuvant therapy, a therapeutic regimen that improves survival in PDAC patients undergoing surgical resection." (PMID 24594697, 2014). "These bone marrow-derived cells were recruited into tumors by the HIF-1 target molecule CXC-chemokine ligand CXCL12 (SDF-1α) released by tumor cells." (PMID 24634660, 2014). "Their research suggested that physiologic, endogenous expression of CXCL12 limits tumor metastasis and participates in the homeostatic turnover of intestinal epithelial cells." (PMID 24810923, 2014). "Kojima and colleagues demonstrated that the acquirement of an activated CAF phenotype by mammary fibroblasts and the associated tumor stimulating properties are related to the activation of TGF-β and CXCL12 autocrine loops." (PMID 24978438, 2014). "The chemokine CXCL12 has been recognized as an important chemoattractant of CXCR4 expressing metastasizing cells of numerous tumor types." (PMID 24390633, 2014). "Node-negative tumours also exhibited increased methylation levels of chemokine ligand 12 gene (CXCL12) and death-associated protein kinase 1 gene (DAPK1) compared with node-positive tumours." (PMID 25052224, 2014). "Our study recognizes MM cells (in addition to BMSCs) as a considerable source of CXCL12 in the tumor niche." (PMID 25526031, 2014). "The target tissues express high levels of CXCL12, allowing tumor cells to directionally migrate to target organs via the CXCL12-CXCR4 chemotactic axis." (PMID 24944647, 2014).
tumor (continued). "Studies in OS mouse models of experimental metastasis, revealed by intravenous injections of tumor cells, indeed demonstrated the relevance of the CXCL12/CXCR4 axis in OS metastasis." (PMID 24390633, 2014). "Cumulatively, these in vivo data reflect the tumor suppressive potential of CXCL12 expression in PDAC cells." (PMID 24594697, 2014). "CXCL12 is primarily produced by stromal cells and is important for the growth, angiogenesis and metastasis of tumor cells." (PMID 25268356, 2014). "For example, the chemokine CXCL12 has been shown to promote tumor growth by affecting breast cancer cell growth and by stimulating the recruitment of endothelial precursor cells (EPCs) into the tumor." (PMID 24734219, 2014). "CXCR4 and CXCL12 play an essential role in tumor growth, metastasis, and cancer cell-microenvironment interaction." (PMID 25471741, 2014). "Although the migration inhibition is only partial (40%), the fact that a higher chalcone concentration (10 μM) inhibits migration by 80%, is clearly in favor of the involvement of CXCL12 via CXCR4 in the tumor cell migration process." (PMID 24629239, 2014). "The CXCL12/CXCR4 axis is known to be involved in several aspects of tumor progression including angiogenesis, metastasis, and survival." (PMID 24674692, 2014). "Another physical and chemical factor, radiation, exerts a similar effect through CXCR4/CXCL12 interaction on tumor angiogenesis." (PMID 25110692, 2014). "Among the family of chemokine and chemokine receptors mediating tumor cell invasion and metastasis, CXCL12/CXCR4 has gained a central role in different types of tumors in mediating tumor growth, angiogenesis and metastasis." (PMID 24472670, 2014). "Immunohistochemical analyses have shown that CXCL12 is highly expressed in hepatic sinusoids including endothelial and Kupffer cells and that disseminating tumor cells express CXCR4." (PMID 24629239, 2014). "In general, tumor-associated DCs (TADCs) can secrete different proangiogenic factors, such as TGF-β, granulocyte macrophage colony-stimulating factor (GM-CSF), CXCL12, or TNFα." (PMID 25254213, 2014). "In a mouse gastric cancer model, CXCL12 expression was found to be enhanced together with enhanced fibrosis in tumor sites." (PMID 24966464, 2014). "Further, CXCL12 reintroduction significantly reduced tumor growth in vitro, with significantly smaller tumors in vivo, leading to a pronounced survival advantage in a preclinical model." (PMID 24594697, 2014). "30D8, a humanized antibody against mouse/human CXCL12, inhibits tumor growth and/or metastasis and improve arthritis in experimental in vitro and in vivo models." (PMID 24904289, 2014). "The data presented in the study demonstrate that CTCE-9908 is efficacious in preventing spread of tumor cells from primary site by inhibiting invasive and angiogenic functions of CXCL12/CXCR4 axis in primary tumor environment." (PMID 24472670, 2014). "CXCR7, the other receptor for CXCL12 (SDF-1), is expressed by many tumor cell lines, and its role as scavenger or co-receptor for CXCL12 remains in debate." (PMID 24723924, 2014). "CXCL12 expression in tumor endothelial cells and CXCR4 expression on metastatic tumors were found to correlate with shorter patient survival, indicative of a more aggressive tumor group." (PMID 24857921, 2014). "As previously detailed, CXCL12 modulates tumor cell proliferation, angiogenesis and metastasis, acting as an autocrine/paracrine growth factor, representing a promising target for the treatment of neoplasia." (PMID 24904289, 2014). "Recovery of the tumor microvasculature is mediated, in part, by CXCL12 and CXCR4, but the role of receptor CXCR7 remains controversial." (PMID 25084358, 2014). "At the transcriptional level, ablation increased Sele, Fgf2, Lifr and Cxcl12 in marrow and decreased Lifr and Sele in the surviving tumor." (PMID 24270800, 2014).
tumor (continued). "In human ovarian carcinomas, CXCL12-recruited pDCs have been shown to produce TNFα and IL-8, favoring tumor angiogenesis." (PMID 25072019, 2014). "In total, our studies reveal novel aspects of CXCL12 function in cancer biology and identify this gene as a multifunctional tumor suppressor that affects both PDAC growth and metastasis." (PMID 24594697, 2014). "The hazard ratio from the survival study was 4.9, reflecting the powerful effect CXCL12 expression imposed on altering the rate of tumor-induced mortality." (PMID 24594697, 2014). "CXCR4 expression was found to be significantly increased in the tumors and correlated with the tumor grade, whereas the expression of CXCL12 was significantly decreased in the tumors compared with the healthy samples." (PMID 24906407, 2014). "In heterogeneous tumor tissue containing both malignant and normal glands, CXCL12 staining was diminished in malignant cells,butpreserved in adjacent normal ductal cells (data not shown)." (PMID 24594697, 2014). "The CXCL12/CXCR4 pathway plays a pivotal role in several aspects of tumor progression including vascularization, metastasis and survival." (PMID 24647809, 2014). "Consistent with a role for CXCL12 as a tumor suppressor, cells producing the chemokine wereincreasingly adherent and migration deficient in vitro and poorly metastatic in vivo, compared to control cells." (PMID 24594697, 2014). "In GBM, CXCR4 and CXCL12 are overexpressed in tumor tissue when compared with normal adjacent parenchyma, and their expression level is correlated with tumor grade and poor prognosis." (PMID 24904289, 2014). "Increased survival in mice with CXCL12-expressing PDAC was correlated not only with decreased primary tumor proliferation but also with the pronouncedabsence of tumor metastasis." (PMID 24594697, 2014). "We observed a 25% increase in total distance and a 23% increase in net distance traveled for MDA-MB-231 tumor cells migrating on aligned nanofiber substrates in the presence of a CXCL12 gradient." (PMID 25385001, 2014). "Together, these data demonstrate a functional tumor suppressive role for the normal expression of CXCL12 in pancreatic ducts, regulating both tumor growth andcellulardissemination to metastatic sites." (PMID 24594697, 2014). "In relation to the tumor microenvironment, pathological involvement of the chemokine (C-X-C motif) ligand 12/chemokine (C-X-C motif) receptor 4 (CXCL12/CXCR4) signaling axis has been very well documented in several malignancies, including PCa." (PMID 25359780, 2014). "Analysis of PDAC tumor tissue revealeda further, and more pronounced,extinction of CXCL12 in CK-19+tumor cells." (PMID 24594697, 2014). "Of direct relevance to our results, increased CXCR4 expression and CXCL12/ CXCR4 signaling promote tumor cell resistance to the chemotherapeutic gemcitabine." (PMID 23442791, 2013). "Blocking CXCL12 inhibited the recruitment of these myeloid-cells in response to RT and subsequently promoted the recovery of tumor vasculature, as well as the regrowth of irradiated tumors." (PMID 24314323, 2013). "The CXCL12/CXCR4 axis was shown to be involved in tumor development and metastatic spread of many cancer types, including OS." (PMID 24040160, 2013). "The present study focused on the biological relevance of CXCR7 in OS in interaction with the CXCR4/CXCL12 axis, reported to promote primary tumor growth and metastasis." (PMID 24040160, 2013). "Induction of MSC migration by tumor cells and stimulation of tumor growth by fibroblasts are dependent on stromal CXCL12 production." (PMID 24064862, 2013).
tumor (continued). "Along these lines, the results of a recently reported study showed that CXCR7 enhanced CXCL12/CXCR4-mediated trans-endothelial migration of tumor cells." (PMID 24040160, 2013). "CXCL12 was highly expressed in the vessels of the primary tumor and to a more limited degree, in the larger vessels of the xenograft." (PMID 23527265, 2013). "In agreement with their findings, our results from the intracranial xenograft model reveal that disrupting the CXCL12/CXCR4 pathway reduces both the vessels that sprout from the tumor core and the intratumoral microvessel density." (PMID 23961808, 2013). "CXCR4, and its ligand CXCL12, regulates chemotactic migration and “homing” of tumor cells to a secondary organ/site, and facilitates tumor cell extravasation." (PMID 24069584, 2013). "Increased tumor cell apoptosis and necrosis has also been observed following impairment of the CXCL12/CXCR4 axis." (PMID 24384839, 2013). "The activation of CXCR4, a G protein-coupled receptor for CXCL12, induced tumor invasion and/or survival of cancer cells." (PMID 24330809, 2013). "Taken together, these studies demonstrate that CXCL12/CXCR4 signaling is a critical event mediating homing of tumor cells and subsequent expansion of metastases." (PMID 23902739, 2013). "CXCL12 in the tumor microenvironment and ascites recruits several different types of immunoregulatory and immunosuppressive cells, including dendritic cells, T regulatory cells, and myeloid derived suppressor cells." (PMID 23372646, 2013). "Akt1-induced CXCR4 expression is active in CXCL12-induced cellular invasion, tumor growth, and intraosseous tumor growth in murine model systems." (PMID 23902739, 2013). "Experimental models of melanoma, colon, pancreatic, thyroid, and prostate cancer have demonstrated that organ directed metastasis is mediated by CXCR4+ tumor cells migrating to CXCL12+ organs such as the liver and the lungs." (PMID 23847541, 2013). "The CXCR4/CXCL12 chemotactic gradient has been proposed as a mechanism for tumor cell homing to distant metastatic sites." (PMID 24278179, 2013). "CXCR4 and CXCL12 are one of the most well studied chemokine systems in tumor growth, metastasis, and angiogenesis." (PMID 23555768, 2013). "CXCR4 promotes tumor progression at different levels of malignancy, including tumor growth, angiogenesis, metastatic dissemination, and homing in CXCL12-enriched cellular niches in metastatic tissues." (PMID 23497377, 2013). "The CXCL12/CXCR4/CXCR7 chemokine axis has been identified as an important element in tumor development, progress and metastasis." (PMID 24074251, 2013).